INS (insulin)
Diseases named in the same sentence as INS in open-access papers (continued):
Sharing a sentence is not in itself a finding about the gene and the disease.
steatosis (continued). "We aimed to evaluate whether two anthocyanins with antidiabetic properties isolated from Maqui can prevent OLZ-induced steatosis in HepG2 liver cells and insulin resistance in L6 skeletal muscle cells." (PMID 34684731, 2021). "This association may be expressed as a feedback loop in which increased hepatic fibrosis and steatosis lead to increased insulin resistance and vice versa." (PMID 33652777, 2021). "Fasting blood glucose levels were significantly higher in NAFLD patients, with fasting insulin levels also being positively related to severity of steatosis (steatosis grade 3 vs. controls: +23.2 mU/L, grade 3 vs. grade 2: +12.7 mU/L, grade 3 vs. grade 1: 16.4 mU/L, p < 0.05 for all comparisons)." (PMID 32151020, 2020). "As previously reported, accumulated fat interferes with insulin signaling pathways and consequently reduces the glucose content taken up from the bloodstream, an effect that is tightly connected to hepatic injury and steatosis in T2DM." (PMID 32194395, 2020). "Its administration to animals can reverse detrimental effects of HFD on adipose tissue content, liver, muscle, and pancreatic islets steatosis as well as an inflammatory profile that subsequently results in increased insulin sensitivity decreased fasting blood glucose and insulin levels." (PMID 32397353, 2020). "In order to evaluate the endocrine activity of Langerhans islets in regulating blood glucose, we analyzed the size and numbers of these islets, as visualized by IF staining for insulin in the steatosis state, and by H&E staining in NASH compared to chow diet-fed mice." (PMID 32093016, 2020). "However, as previously demonstrated by our group, this model of genetic IR was characterized by higher insulin levels and HOMA-IR, and was associated with increased steatosis and liver fibrosis accumulation, even independently of hepatic inflammation." (PMID 31671785, 2019). "The progression from NAFLD to NASH in humans was originally proposed as a “two-hit hypothesis”, in which insulin resistance mediated increase of free fatty acids due to enhanced lipolysis was the first hit that leads to steatosis." (PMID 31795276, 2019). "Adipocyte specific KO of PU.1 resulted in decreased liver inflammation, decreased steatosis and significantly improved liver insulin sensitivity compared with fl/fl controls, as revealed by both hyperinsulinemic-euglycemic clamp and acute insulin signaling studies." (PMID 31611602, 2019). "Moreover, a number of animal and cell studies showed that LR therapy improved hepatic insulin resistance and lipogenesis-induced lipid accumulation and decreased steatosis and even fibrosis." (PMID 31236111, 2019). "Exposure of cancer cell lines to saturated (typically palmitate) or unsaturated (typically oleate) long chain fatty acids results in steatosis accompanied by upregulation of cytokines, interruption of insulin signalling, increased reactive oxygen stress and apoptosis signalling." (PMID 29786565, 2018). "The reduced steatosis is beneficial for improving insulin sensitivity." (PMID 30081580, 2018). "However, in the present study, HOMA-IR, reflecting hepatic insulin sensitivity, was more strongly correlated with hepatic necroinflammatory activity than with steatosis grade." (PMID 29749571, 2018). "In summary, the present study indicates that the 3D liver spheroid system elicits many in vivo phenomena such as insulin resistance and, importantly, reversibility of steatosis, which makes the system suitable for the study of lipid droplets in biology and disease." (PMID 30250238, 2018). "As steatosis leads to decreased hepatic insulin sensitivity and increased gluconeogenesis, it has been hypothesized that NAFLD precedes the development of T2DM." (PMID 29151224, 2018).
steatosis (continued). "However, taken individually, they reflect only one aspect of the NAFLD pathological scenery, i.e., hepatocyte apoptosis, inflammation, fibrosis, insulin sensitivity, and steatosis." (PMID 29463024, 2018). "TNF-α interferes with insulin signaling, thereby favoring steatosis, and may play a pro-inflammatory role in the pathogenesis of NAFLD." (PMID 30110395, 2018). "This improvement in insulin sensitivity could have a secondary effect of improving steatosis and steatohepatitis." (PMID 28419124, 2017). "Similarly, RARβ2 agonists improved insulin sensitivity, lowered serum glucose and insulin levels, and reduced triglycerides and steatosis in the liver, pancreas, and kidneys of obese and diabetic mice." (PMID 29286303, 2017). "In addition, gender differences in insulin sensitivity, WD-induced steatosis, and predicted microbiota functions were FXR-dependent." (PMID 28496104, 2017). "The B-13/H cell irreversibly accumulated triglycerides (steatosis) in a time- and dose-dependent manner when exposed to fatty acids, an effect that was potentiated by the combined addition of hyperglycaemic levels of glucose and insulin." (PMID 28552552, 2017). "Of the 19 variables previously identified, 12 were included in the final steatosis phenomic classifier including glucose, serum insulin, triglycerides, HDL, ALT, ferritin, creatinine, chloride, zinc, use of metformin, use of estrogen/progestin, and a clinical diagnosis of sleep apnea." (PMID 28266614, 2017). "In this study, we used a high-fat atherogenic diet (60% fat, 1.25% cholesterol, and 0.5% cholate) to induce a more severe form of NASH, as this diet induces hepatic insulin resistance, progressive steatosis, inflammation, and fibrosis over 6 to 24 weeks, mimicking the human disease pathology." (PMID 28042486, 2016). "Augmented FA oxidation and improved insulin sensitivity may have additionally contributed to protection from steatosis." (PMID 27181051, 2016). "In our study, the reduction of serum levels of uric acid was associated with improvement on the grade of steatosis, but was not accompanied by alterations of the insulin levels or HOMA-IR." (PMID 27367724, 2016). "This study found that phosphatidic acid is up-regulated in serum during the progression from HU to HU+NAFLD, which suggests that oxidative stress and insulin resistance due to up-regulated phospholipase metabolism appear at least partially responsible for the development of steatosis in HU." (PMID 26890003, 2016). "Paradoxically, insulin-stimulated hepatic lipogenesis through SREBP-1c induction is not impaired in steatosis-associated insulin resistant livers." (PMID 26067236, 2015). "Finally, the effects of insulin-sensitizing drugs rosiglitazone and pioglitazone include reversal of steatosis, suggesting that to some extent steatosis was responsible for insulin resistance." (PMID 26107182, 2015). "Therefore hepatic inflammation, steatosis and disrupted insulin signaling potentially contribute to the metabolically compromised phenotype that presented in the HF3 fetuses." (PMID 26343716, 2015). "NASH may arise through a “two-step” process in which insulin resistance first produces steatosis and subsequently oxidative stress drives inflammation." (PMID 24958099, 2014). "The improvement of insulin sensitivity by LY could reduce the free fatty acid flux to the liver that contributes to steatosis." (PMID 25295245, 2014). "Thus, in addition histopathological findings, such as fibrosis and steatosis, cytokines and metabolic factors, such as insulin resistance, are involved in decreased hepatic TBF in NASH." (PMID 24424317, 2014). "In this context, the liver of an extremely obese patient with severe steatosis might behave as if there were total insulin resistance, which could be responsible for the downregulation of the lipogenic pathway shown in the liver of these patients." (PMID 25474087, 2014).
steatosis (continued). "The complex interplay between virus, steatosis, and insulin sensitivity may influence obtained results." (PMID 25121101, 2014). "Proteomics revealed reduced AKT/mTOR signaling in fibroblasts derived from steatosis patients and further establishes that the insulin-resistant phenotype is present not only in insulin-metabolizing central organs, e.g., the liver, but is also manifested in skin fibroblasts." (PMID 22969728, 2012). "Misregulation of inflammatory cytokine, adipokine, and chemokine signaling may reinforce the initial mechanisms of ROS production and insulin resistance, representing determinant factors in the progression of steatosis to steatohepatitis." (PMID 23304111, 2012). "The livers of insulin-treated mice had a dose-dependent decrease in steatosis by oil red-O." (PMID 22745692, 2012). "In line with earlier studies demonstrating that subcutaneous administration of long-acting GIP analogues resulted in improved β-cell function and glycemic control, GIP Tg mice showed improved insulin sensitivity, glucose tolerance and β-cell function, as well as reduced steatosis." (PMID 22802954, 2012). "Potential mechanisms of this effect may include the increased sensitivity of steatotic livers to oxidative stress, cytokine-mediated injury, and steatosis-related hepatic insulin resistance." (PMID 21854603, 2011). "Moreover, PPARγ itself is required in a majority of metabolic tissues for regulation of insulin action and normal physiologic response to nutrients and it plays a critical role in the development of steatosis." (PMID 20981297, 2010). "Notably, FXR agonists, exemplified by OCA, have demonstrated efficacy in ameliorating liver fibrosis (with improvements of at least one grade) and reducing steatosis levels by enhancing insulin sensitivity and modulating the bile acid–glucose–lipid metabolism axis." (PMID 40807240, 2025). "In the early stage of MAFLD, liver tissue is mainly characterized by simple steatosis and mild inflammatory infiltration, and the level of inflammation in this stage increases rapidly with the accumulation of lipids in the liver and the intensification of insulin resistance." (PMID 41357179, 2025). "Steatosis is commonly induced in vitro using various methods, such as incubating cells in media containing a combination of sodium palmitate and sodium oleate, or by pre-incubating cells in starvation media followed by incubation in high-glucose media with 30 mM glucose and 100 nM insulin." (PMID 40981229, 2025). "Insulin-deficient signaling states directly correlate with concurrent elevations of some sphingolipid species in subjects with MASH, suggesting that these lipids may play a role during progression from simple steatosis to MASH." (PMID 38962680, 2024). "It has been reported that persistent moderate or severe steatosis after BS is more frequently observed in patients who have maintained a higher insulin resistance index (1/QUICKI) than in patients who have improved their insulin resistance index (44% vs. 20.2%; p = 0.04)." (PMID 37513605, 2023). "Interestingly, amongst the insulin independent recipients in this cohort, those with hepatic steatosis also had higher serum C-peptide levels, suggesting that better functioning grafts produced more steatosis through paracrine action." (PMID 37711891, 2023). "Although blocking S273 phosphorylation could be a promising therapeutic strategy to improve insulin sensitivity, this modification also affects other pathways in the organism, especially those related to steatosis and glycogen metabolism, resulting in unbalanced pancreatic hormones and liver damage." (PMID 37189379, 2023). "Therefore, we next monitored whether the liver steatosis induced by hepatocyte Hmgb1 deletion has any effect on glucose homeostasis and/or insulin signaling in mice subjected to HFD60%." (PMID 35333579, 2022).
steatosis (continued). "Interestingly, lower body weight of APP23 mice may partially protect from diet-induced metabolic stress depicted by extenuated steatosis and adipocyte hypertrophy, which seem to contribute to improved insulin sensitivity." (PMID 33864446, 2021). "The severe consequences resulting from steatosis presence in CHC including increased risk of hepatic fibrosis and/or HCC, as well as decreased virologic response to antiviral therapy, all stress the urgency of investigating the complex derangements in host insulin and lipid metabolism." (PMID 34680608, 2021). "An increase in the expression of insulin along with ameliorated insulin signaling in glucoregulatory organs such as the liver, muscle and adipose tissue can intensify glucose uptake and metabolism, and consequently reduce hepatic gluconeogenesis and improve steatosis." (PMID 31540136, 2019). "Plasma insulin was found to be correlated with higher inflammatory tone in perigonadal (r = 0.64, p < 0.001) and mesenteric fat depots (r = 0.56, p < 0.001), and microvesicular steatosis (r = 0.56, p < 0.001) in male mice further supporting the use of male mice as a model for NAFLD/NASH." (PMID 31405127, 2019). "Whereas some models suggest a defined, successive cascade in the etiology of liver disease (steatosis and hepatic insulin resistance leading to steatohepatitis, which may lead to fibrosis/cirrhosis, and ultimately to HCC), other reports paint a less clear picture." (PMID 29558460, 2018). "Since many previous studies have proposed that autophagy plays an important role in NASH development, we hypothesized that increasing the MCFA/LCFA ratio may protect hepatic cells against LCFA-induced steatosis, insulin resistance, and lipotoxicity by regulating autophagy." (PMID 29070903, 2017). "Similarly, high glucose intake primarily caused increased glycogenesis rather than steatosis in insulin sensitive individuals." (PMID 27632189, 2016). "Additionally, classical complications by insulin signaling also were presented: increases in glycogen levels were observed in liver, muscle, heart, and kidney in cortex and medulla zones, and steatosis in the evaluated tissues (triglycerides stored) was also observed." (PMID 27119007, 2016). "Based on the notion that insulin and activation of Akt are known to induce lipid storage in the liver, sustained hepatic Akt activation could be expected to lead to an increase in steatosis." (PMID 26655903, 2015). "Additionally, oxidative damage induced by the HCV core protein may simultaneously induce steatosis and impair insulin signaling in the hepatocyte." (PMID 25367448, 2014). "We propose that in the presence of high MUFA content, the population of alternatively activated resident liver macrophages may mediate the beneficial effects on liver insulin sensitivity and alleviate the metabolic disturbances imposed by a HF diet feeding and steatosis." (PMID 22439764, 2012). "Nevertheless, studies carried out on a mice model of liver diacylglycerol acyltransferaze-2 overexpression exhibiting severe steatosis but normal hepatic insulin sensitivity showed that steatosis per se could be dissociated from the onset if hepatic insulin resistance." (PMID 22439764, 2012). "We propose that in the presence of a high MUFA content the population of alternatively activated resident liver macrophages may mediate beneficial effects on liver insulin sensitivity and alleviate the metabolic disturbances imposed by HF diet feeding and steatosis." (PMID 22439764, 2012). "The improvement in insulin sensitivity and the consequent low er flow of free fatty acids to the liver, together with the increase in adiponectin (a cytokine with hepatoprotective and anti-inflammatory effects), could be key factors contributing to the reduction in steatosis and liver inflammation." (PMID 41471698, 2025). "In the diet-induced steatosis mouse model, inhibiting hepatic ASPG expression improved glucose tolerance and systemic insulin signaling transduction." (PMID 40760121, 2025).
steatosis (continued). "Common readouts include histological grading of steatosis, serum liver enzymes (ALT, AST), inflammatory cytokines (e.g., TNF-α, IL-6), insulin resistance indices, and gut microbiota profiling via 16S rRNA sequencing or metagenomics." (PMID 41001122, 2025). "Conversely, the overexpression of SELENOS in hepatocytes reduced steatosis and improved insulin sensitivity, highlighting the importance of SELENOS in lipid metabolism and insulin signaling." (PMID 39942544, 2025). "In an HFD-induced steatosis mouse model, the aqueous extract improved insulin sensitivity, increased adiponectin levels, and increased PPAR-mediated fatty acid oxidation, demonstrating its liver-protective properties against steatosis." (PMID 39594531, 2024). "FH mice are overtly obese, insulin resistant and exhibit severe fibrosing MASH whereas WH and FN are moderately obese and insulin resistant and exhibit steatosis with moderate levels of inflammation and cell injury but inconspicuous fibrosis." (PMID 39206703, 2024). "As the liver is the primary metabolic organ in the body, and we observed different insulin sensitivities between HFHSD- and HFHSD+CUR-fed mice, we then decided to evaluate if it has any influence on hepatic lipid homeostasis and steatosis in the liver of mice." (PMID 39056667, 2024). "Age, glucose levels, insulin levels, HOMA-IR values, cholesterol, and triglyceride levels were significantly higher in steatosis plus NASH group than in the control group." (PMID 38265508, 2024). "Our results indicated a potential protective effect of α-lipoic acid on the disturbances in the sphingolipid metabolism and insulin transduction under HFD, which protects from steatosis deterioration." (PMID 38794739, 2024). "EV-treated mice showed reduced levels of steatosis, liver damage (AST, ALT), liver triglycerides, total cholesterol, hepatic expression of TNF-α, IL-1, and IL-6, and restored insulin sensitivity." (PMID 39767754, 2024). "Primary:6 and 12-month changes in steatosis (CAP) and fibrosis (liver stiffness).Secondary:Alterations in hepatic enzymes, insulin resistance, and lipid profile at 6 and 12 months." (PMID 37601777, 2023). "In HepG2 cells with steatosis, PGAM5 knockdown reduced insulin sensitivity, increased mTOR phosphorylation and reduced the expression of NRF2, catalase (CAT), HO-1 and GPX6." (PMID 37605246, 2023). "In the mild steatosis group, the BMI value and serum levels of ALT, ALP, UA, TC, APOB, and insulin were higher than that in control group (all P < 0.05)." (PMID 34986792, 2022). "In line with reduced adiposity and improved insulin sensitivity, FMTRYGB animals showed improved steatosis, reduction in lipid levels, and a switch to a dominant anti-inflammatory cytokine profile compared to HF-DIO controls." (PMID 35739571, 2022). "A positive correlation between plasma insulin levels and hepatic CD36 expression was observed in insulin-resistant patients with steatosis." (PMID 34327606, 2022). "IXA4 treatment improves systemic glucose metabolism and liver insulin action through IRE1-dependent remodeling of the hepatic transcriptome that reduces glucose production and steatosis." (PMID 35105890, 2022). "Previous studies have shown that in the HepG2 steatosis cell model, liver-targeted Gal-OSL/Res nanocarriers can effectively reduce liver lipid accumulation and reduce insulin resistance by regulating AMPK/SIRT/FAS/SREBP1c signaling pathway." (PMID 35907871, 2022). "Taken together, our findings have revealed that excessive fructose intake-mediated steatosis under HSuD, NCFD, and/or HFFD conditions involved insulin intolerance, increased TAG, and decreased HDL accumulation in the liver, depending on TM4SF5 expression." (PMID 35123128, 2022). "Consistent with the histological steatosis effects, FFD markedly increased intrahepatic diacylglycerols (DAGs), a lipid that blocks insulin action at the level of its receptor." (PMID 35830259, 2022).